MMP1 (matrix metallopeptidase 1)
Diseases named in the same sentence as MMP1 in open-access papers (continued):
Sharing a sentence is not in itself a finding about the gene and the disease.
emphysema (continued). "In the present study we quantified MMP-1 expression within the lung by immunohistochemistry and related MMP-1 expression to histological and computed tomography (CT) measures of emphysema in order to better evaluate the pathogenic role of this enzyme." (PMID 24792232, 2014). "Our findings show that the macrophages in smokers’ lungs express increased MMP-1 and, furthermore, that the number of positive macrophages increases with the severity of emphysema." (PMID 24792232, 2014). "Although MMP-1 staining was increased in all smokers, there was significantly more staining of alveolar macrophages in individuals with a higher emphysema score." (PMID 24792232, 2014). "When MMP-1 is present, as is seen in both human emphysema as well as in the smoke-exposed rabbit, TLR4 activation by cigarette smoke ultimately leads to expression of the collagenase MMP-1." (PMID 23450717, 2013). "Though MMP-1 was elevated in both the normal smoker and emphysema groups, collagenase activity was only increased in the emphysema subjects." (PMID 23441181, 2013). "Baseline BALF and plasma MMP-1, -9 and -12 levels correlated poorly with follow up measurements performed 3 to 6 months later despite the fact that the emphysema subjects were in a stable disease state." (PMID 23441181, 2013). "Though MMP-1 levels were comparable in smokers and emphysema subjects, only those with emphysema had significantly increased collagenase activity." (PMID 23441181, 2013). "With the development of genetically modified animals, researchers have been able to better define the contribution of isolated pathways in emphysema pathogenesis, including the interstitial collagenase MMP-1." (PMID 23450717, 2013). "Such a finding however is not surprising since the results of the basic studies suggest that MMP-1 expression is critical in the pathogenesis of lung destruction and generation of the emphysema phenotype." (PMID 22992122, 2012). "In 1992 D’Armiento and coworkers found that over-expression of human MMP-1 (interstitial collagenase) in transgenic mice led to the development of emphysema." (PMID 22992122, 2012). "The exosomes released from BECs (broncho epithelial cells) exposed to chronic exposure are shown to bear extracellular matrix-associated CCN-1 (Cellular communication factor 1) protein, which induces MMP-1 (Matrix metalloproteinase 1) secretion leading to emphysema formation eventually." (PMID 35008971, 2022). "In contrast to a protective role of the three upregulated genes, collagenase MMP1 may play a causative role in the development of COPD, because MMP1 overexpression is sufficient to cause pulmonary emphysema in vivo." (PMID 30626320, 2019). "The expression of MMP1 is related to many diseases, including emphysema and malignant tumors." (PMID 31275410, 2019). "One such study used a transgenic mouse line with lung-specific expression of matrix metalloproteinase (MMP)-1 to show that emphysema could develop through an elastin-independent mechanism." (PMID 27462275, 2016). "Indeed, MMP-1 expression was upregulated in bronchoalveolar lavage fluid from patients with emphysema." (PMID 27455234, 2016). "Furthermore, we evaluated the gene expression not only for metalloelastase 12 but also for collagenases MMP-1, -8 and 13 to better understand the role of collagenases in emphysema development and progression, which remain understudied." (PMID 26052708, 2015). "Our laboratory has demonstrated a major role for MMP-1 in the development of emphysema." (PMID 25664615, 2015). "They suggested that the loss of collagen III was a greater determinant of emphysema than the loss of collagen I. It is likely that we did not observe an up-regulation for MMP-1 gene expression because we used wild type animals in this experimental model." (PMID 26052708, 2015).
emphysema (continued). "In summary, our findings further support the proposal that inflammatory cells (alveolar macrophages), as well as type II pneumocytes and airway epithelium, are a significant source of MMP-1 and that this enzyme plays a role in the pathogenesis of emphysema, even after smoking cessation." (PMID 24792232, 2014). "MMP-1 is induced in smokers with COPD and its overexpression in mice causes emphysema." (PMID 24447332, 2014). "In addition, the results are concordant with our previous finding of a significant relationship between MMP-1 mRNA expression by alveolar macrophages and the extent of emphysema measured by CT scan." (PMID 24792232, 2014). "Over expression of MMP-1 leads to emphysema in animal models." (PMID 24447332, 2014). "Enzyme-linked immunosorbent assay and luminex assays measured MMP-1, -9, -12 and tissue inhibitor of matrix metalloproteinase-1 in the BALF and plasma of non-smokers, smokers with normal lung function and moderate-to-severe emphysema subjects." (PMID 23441181, 2013). "MMP-1 is up regulated in alveolar walls and macrophages in human emphysema and the transgenic expression of human MMP-1 in mice, which lack the gene for MMP-1, generates adult-onset emphysema, associated with a loss of lung compliance." (PMID 23441181, 2013). "Mice do not even have the gene for MMP-1, a key protease implicated in human emphysema pathogenesis." (PMID 23450717, 2013). "Furthermore, several polymorphisms in MMP1, MMP9, and MMP12 genes have been associated to emphysema and related phenotypes." (PMID 23734748, 2013). "The strength of these animal studies was extended when follow-up studies demonstrated that indeed MMP-1 expression was increased in the lung parenchyma of patients with emphysema and that cigarette smoke directly induced expression of MMP-1 in pulmonary small airway epithelial cells." (PMID 23450717, 2013). "On the one hand MMP-13 may still help to limit ECM deposition in areas of dense fibrosis, on the other hand excessive MMP-13 activities in the airways may promote development of honeycomb cysts, similar to the induction of emphysema formation in MMP-1 overexpressing mice." (PMID 24023851, 2013). "Therefore, we hypothesized that exposure to TiO2 NPs could lead to and/or aggravate pre-existing pulmonary emphysema, given the roles of MMP-1 and MMP-12 in the pathophysiology of the disease." (PMID 22849372, 2012). "Even though the majority of animal models of emphysema have reinforced the importance of MMP-12, there are many studies in patients who implicate the importance of collagenases, such as MMP-1, -8 and -13 in this disease." (PMID 26052708, 2015). "Although transgenic upregulation of MMP-1 in mice leads to emphysema, knockout of the MMP-12 gene prevents the development of emphysema in mice exposed to cigarette smoke, implicating both of these proteases in the process." (PMID 24792232, 2014). "MMP-1 and MMP-9, major members of MMPs, contribute to the development of cigarette-induced emphysema." (PMID 23555986, 2013). "The collagenase MMP-1, the gelatinase MMP-9 and the metalloelastase MMP-12 are of particular interest in emphysema pathogenesis." (PMID 23441181, 2013). "Subsequent studies demonstrated that the important target for MMP-1 was type III collagen and that adult-onset emphysema developed in strains of mice expressing MMP-1 in the lung." (PMID 22992122, 2012). "Transgenic mice over-expressing MMP-1 develop emphysema, whilst MMP-12 knockout mice are protected from emphysema despite prolonged cigarette smoke exposure." (PMID 23228114, 2012). "Matrix metalloproteinase-1 (MMP-1) plays a role in tissue remodeling during development, inflammation, migration of inflammatory and malignant cells, and COPD and emphysema pathogenesis." (PMID 21245013, 2011). "Elevated protein levels of MMP-1, MMP-8 and MMP-9 were found in BALF or lung parenchyma of patients with emphysema." (PMID 16316467, 2005).
emphysema (continued). "Moreover, SIRT1 overexpression, by downregulation of MMP-1 and MMP-3, has beneficial effect on mice emphysema and human COPD." (PMID 33917352, 2021). "CS-related TLR4 signaling was shown to increase MMP-1, a crucial actor in emphysema, in a MyD88- and IRAK1-dependent manner, while CS-exposed TLR4–/– mice were protected from emphysema, impaired lung function, airway fibrosis, and collagen deposition in small airways as compared with wild-type mice." (PMID 34248677, 2021). "A limitation of this study is the use of bacterial collagenase rather than a more physiologically relevant enzyme such as MMP-1 which has been shown to be present in increased concentrations in humans with late-stage emphysema." (PMID 27462275, 2016). "Increased MMP-1 and MMP-9 levels have been detected in BALF of emphysema patients." (PMID 26770019, 2015). "Indeed, increased lung concentrations of NE, MMP-1, MMP-9, and MMP-12 have been found in CS-exposed mice and emphysema patients, and thus excessive proteolytic activity must be tightly regulated." (PMID 25962837, 2015). "Previously, when MMP-1 expression in the lungs of smokers with emphysema was compared to that of nonsmokers, substantial differences were found in MMP-1 expression by alveolar macrophages and type II pneumocytes." (PMID 24792232, 2014). "Unfortunately, the study was limited by the small number of subjects (only two) who were long-term smokers but had normal lung tissue and therefore they were not able to compare the expression of MMP-1 in smokers with and without emphysema." (PMID 24792232, 2014). "In this study we focused on MMP-1 because of its ability to degrade type III collagen, the major structural component of the alveolar ducts and septa, which are key regions subjected to proteolytic destruction in emphysema." (PMID 24792232, 2014). "Analyses between paired groups showed that MMP-1 and -9 levels in smokers and emphysema subjects were significantly increased compared to non-smoking controls." (PMID 23441181, 2013). "It has been shown that transgenic mice over-expressing MMP1 or MMP9 develop pulmonary changes comparable to human emphysema, and that mice lacking the MMP12 gene are protected from emphysema despite a long term exposure to cigarette smoke." (PMID 23734748, 2013). "In addition to MMP9, several animal and genetic studies have connected MMP1 and MMP12 to COPD and emphysema." (PMID 23734748, 2013). "We did not, however, find any associations between the MMP1 and MMP12 SNPs and emphysema or lung functions decline." (PMID 23734748, 2013). "In humans, increased levels of MMP-1, localized within the resident alveolar epithelial cells, have been reported in the lungs of patients with emphysema but not in normal controls." (PMID 22992122, 2012). "Transgenic mice over-expressing MMP-1 develop emphysema, whilst MMP-12 knockout mice are protected from emphysema despite prolonged cigarette smoke exposure, implicating MMP-12 as a compelling emphysema determinant in this model." (PMID 20078883, 2010). "Interestingly, the progressive increase in cCNN1 during CS exposure induced MMP1 secretion while decreasing that of VEGF, implying a role for CCN1 in elevating MMP1 and down-regulating VEGF, alterations which have been well documented in inducing emphysema." (PMID 36613669, 2022). "This addresses the question of whether smokers who develop emphysema have increased expression of MMP-1 relative to smokers who do not." (PMID 24792232, 2014). "Similarly, there were more MMP-1-positive alveolar macrophages and type II pneumocytes in subjects with more severe emphysema, not simply more cells." (PMID 24792232, 2014). "Since it is well-documented that MMP-1 is fundamental to emphysema pathogenesis, the rabbit is the ideal species to examine when exploring the MMP-1 regulated lung destruction and determining if pharmacological inhibition of MMP-1 is a feasible approach to the treatment of emphysema." (PMID 23450717, 2013).
emphysema (continued). "Furthermore, due to our limited sample size, we were not able to fully examine the relationship between MMP-1 expression and all of the GOLD stages of disease or grades of emphysema." (PMID 24792232, 2014).
Arthritis (43 papers, 2008 to 2025). Inflammation of a joint. "To determine the specific activity of key MMPs implicated in arthritis, we performed ELISAs for MMP1, MMP3, and MMP13." (PMID 40491903, 2025). "MMP1 plays a clinically important role in inflammatory diseases and has been associated with many pathological processes, including wound healing, tumor metastasis and arthritis." (PMID 36120307, 2022). "However, MMP1 overexpression is associated with several pathological musculoskeletal conditions, such as arthritis and tendinopathies." (PMID 32650441, 2020). "Many studies have provided evidence for an association between the MMP-1 gene and arthritis." (PMID 27245218, 2016). "MMP1 plays a clinically important role in inflammatory disease, and has been implicated in numerous pathological processes including wound healing, tumour metastasis and arthritis." (PMID 21244711, 2011). "For arthritis, iguratimod has been demonstrated to inhibit serum MMP-1 and MMP-3 of RA patients; while in bleomycin-induced interstitial lung disease, iguratimod increased the level of MMP-9 of lung tissues." (PMID 37596660, 2023). "In the present study, we observed chondroprotective effects in an animal model of arthritis and selective suppression of MMP-1/MMP-3 in RASFs using a CDK4/6 inhibitor." (PMID 34849618, 2022). "Previous data showed intraarticular salmon CT to reduce arthritis in vivo and suppress the expression of MMP1, 3 and 13, all enzymes enhancing collagen fiber degradation." (PMID 35036874, 2022). "The antioxidant and anti-inflammatory properties of melatonin and 5-MTX in arthritis models have demonstrated that the protective effect is created by reducing the expression of MMP-1 and MMP-2." (PMID 33628825, 2021). "Other studies have shown increased MMP-1 and cathepsin K expression in arthritis." (PMID 36839155, 2023). "In this study, CFA treatment caused the high expression of mmp1 in cartilage and brain in mice, and andaliman extract and nanoandaliman as an alternative arthritis treatment significantly suppressed inflammatory arthritis symptoms in mice via reducing mmp-1 gene expression." (PMID 36429168, 2022). "Our data demonstrated that nanoandaliman at low dose (25 mg/kg bw) showed a significant effect on suppressing the expression of cox-2, il-1b, inos, and mmp1 genes, indicating its potency as an anti-arthritic and anti-inflammatory agent for the management of arthritis." (PMID 36429168, 2022). "Moreover, our preliminary study verified the cytokines (TNF-α, IL-1β) and inflammatory mediators (MMP-1, MMP-3) associated with joint inflammation in animal models." (PMID 34190191, 2021). "However, it was shown that murine MMP1 is involved in various types of cancer, sepsis, and arthritis in mice." (PMID 32075290, 2020). "In addition, transcripts for MMP1 and ADAMTS4 (encoding proteases which degrade extracellular matrix proteins of cartilage and are found in the synovial fluid of injured and arthritis knees) were increased in the synovium in this same post-operative period." (PMID 32107493, 2020). "In addition, several transcripts with known roles in arthritis were positionally enriched in specific joint locations including MMP1, MMP13, interleukin (IL) 1R, IL34 and CXCL12 (refs 17, 18, 19, 20)." (PMID 28332497, 2017). "The in vitro data obtained in this study shows that chondrocytes treated with celecoxib produce fewer arthritis-associated mediators such as PGE2 and MMP-1 than chondrocytes treated with piroxicam or prednisone and more anabolic indicators, namely, CII and aggrecan." (PMID 26000299, 2015). "Among these DEGs are MMP1 and MMP19, which are proteins linked to the breakdown of extracellular matrix (ECM) in normal physiological (embryonic development, reproduction, and tissue remodeling) and disease processes (arthritis, cancer metastasis, and HIV pathogenesis)." (PMID 31484431, 2019).
Arthritis (continued). "All of these beneficial impacts of DAPA were reflected in the improvement of AI, gait score, and paw swelling, along with the reduced levels of RF, MMP-1, and MMP-3 arthritis markers." (PMID 40350466, 2025). "MiRNA-20a targets TXNIP to inhibit the activation of NLRP3, ASC and caspase-1 in adjuvant-induced arthritis FLS and to suppress the secretion of IL-1 and MMP-1." (PMID 37426634, 2023). "TGP can also inhibit joint destruction in rats with collagen-induced arthritis by decreasing the secretion or production of vascular endothelial growth factor (VEGF), basic fibroblast growth factor (bFGF), MMP-1, and MMP-3 from fibroblast-like synoviocytes." (PMID 35186100, 2022). "Interstitial collagenase (MMP-1), stromelysin-1 (MMP-3), and collagenase 3 (MMP-13) appear to degrade the components of the cartilage ECM in arthritis." (PMID 32937098, 2021). "In vivo, the inhibition of TRAF6 using mice-specific TRAF6 siRNA inhibit serum anti-collagen II antibodies, MMP-1, MMP-3, and MMP-9, thereby reducing the severity of arthritis and joint inflammation." (PMID 33294443, 2020). "The induction of MMP1 in response to TNF was significantly larger in knee compared with upper extremity SFs, showing that not only basal expression of arthritis-relevant molecules, but also the response to TNF differs between joints." (PMID 28332497, 2017). "In synovial fibroblasts from arthritis patients, HDAC1 siRNA enhanced TNFα-induced MMP-1 expression, whereas HDAC4 was identified as a negative regulator of MMP-1 expression." (PMID 28596772, 2017). "To further validate the mechanism by which MFK902 suppressed arthritis progression, we examined the transcript expression of chemokines (CCL2), adhesion molecules (VCAM-1), MMPs (MMP-1 and -3), and RANKL by semi-quantitative RT-PCR." (PMID 27741237, 2016). "IFN-γ also inhibits IL-1b-mediated production of MMP-1 and MMP-3 by synovial fibroblast in the early phase of arthritis." (PMID 23613752, 2013). "When calcitriol is used in the treatment of knee osteoarthritis, it can inhibit MMP by inhibiting MMP-1, MMP-3, and MMP-13 gene expression, thereby reducing the severity of arthritis in patients, reducing pain in patients, and improving the living conditions of patients." (PMID 36091601, 2022). "Therefore, the identification of IL-33 as a stimulus of MMP-1 and MMP-13, and the elucidation of its mechanisms of induction and action, provide new insights into the promotion of arthritis responses by the innate immune system." (PMID 29095435, 2017). "In a mouse model of arthritis, TSA also inhibited MMP-1, -3, and -13 expression." (PMID 28596772, 2017). "Serum concentrations MMP-1, MMP-3, and MMP-9, acutely adapt to mechanical loading, with rapid increases at the beginning of physical activity followed by a fairly rapid stabilization thereafter; moreover, MMP-2, MMP-3, and MMP-9 are highly expressed in patients afflicted by arthritis." (PMID 36835076, 2023). "The findings of the existing trial showed that CFA injections increased the serum levels of MMP-1 and cathepsin K, with a significant concomitant reduction in osteocalcin; these findings concur with other reports of high expressions of MMP-1 and cathepsin K in arthritis." (PMID 36839155, 2023). "The analysis showed that MMP1 was mainly involved in extracellular matrix breakdown in normal physiological processes (such as: embryonic development, reproduction and tissue remodeling) as well as in disease processes (such as: arthritis and metastasis)." (PMID 36120307, 2022). "Notably, this anti-inflammatory effect of PPARγ ligands extends to the inhibition of IL-1β-induced expression of MMP-1 and MMP-13 in rabbit chondrocytes, and administration of these compounds blunts the development of joint disease in animal models of arthritis." (PMID 19046432, 2008).